STAT3 (signal transducer and activator of transcription 3)
Diseases named in the same sentence as STAT3 in open-access papers (continued):
Sharing a sentence is not in itself a finding about the gene and the disease.
Stroke (continued). "Moreover, blocking STAT3 activation partially abolished iMSC-sEV’s inhibition of stroke-induced autophagy and angiogenesis." (PMID 32698909, 2020). "Further investigation to elucidate the thorough functions of STAT3 after stroke is in need." (PMID 32698909, 2020). "STAT3p and Arg1 expressions were unchanged early after stroke, suggesting that the MDSCs are at least theoretically able to suppress immune responses as both the phosphorylated transcription factor STAT3 as well as the enzyme Arg1 are essential for anti-inflammatory MDSC function." (PMID 33329318, 2020). "Endothelial Stat3 is essential for long-term recovery after stroke for its regulations on angiogenesis, axon growth and ECM-remodeling which might serve as a potential target for stroke treatment via fostering angiogenesis and neuroregeneration." (PMID 31434962, 2019). "However, the exact mechanism through which astrocytic endothelin-1 affects the Jak2/Stat3 pathway in a murine stroke model need would benefit from further investigation in the future." (PMID 31733648, 2019). "Overall, the findings of the present study further confirmed our hypothesis that astrocytic endothelin-1 overexpression promotes neural progenitor cell proliferation and differentiation into more astrocytes after stroke via the Jak2/Stat3 pathway." (PMID 31733648, 2019). "Previous studies investigated that activated STAT3 in stroke model could promote numerous genes which play a protective effect on neural injury and repair." (PMID 31827699, 2019). "Stat3 is a transcription factor which is upregulated after stroke." (PMID 29516010, 2018). "Studies have shown that the activation of the JAK2/STAT3 pathway after experimental stroke could improve functional performance and/or decrease cell apoptosis." (PMID 28848617, 2017). "Moreover, to our best knowledge, this is the first study to provide evidence that changes of STAT3 activities located in microglia involve Hcy-induced microglia activation and inflammation responses following stroke." (PMID 28923114, 2017). "Some findings suggest that treatments that activate the STAT3 signaling after experimental stroke may lead to improved functional performance and/or decreased cell death." (PMID 28923114, 2017). "In addition to increased IL-21 expression after stroke, we also found increased phosphorylated STAT3 which was decreased with decernotinib treatment." (PMID 28790974, 2017). "The importance of Stat3 expression after stroke and neonatal HIE has been controversial." (PMID 27683877, 2016). "Along this line of evidence, IL-18 after stroke is produced by microglia and contributes to fibrosis in the aged rat brain via STAT3 activation, leading to a large accumulation (237-fold over controls) of collagen III (Col3a1) transcripts that are normally expressed in adventitial fibroblasts." (PMID 24672479, 2014). "Research indicates that inhibiting STAT3 activation could be a therapeutic target post‐stroke." (PMID 40715012, 2025). "We revealed that kaempferol regulates post-stroke apoptosis and neuroinflammation involved by neutrophils, and the underlying mechanism may be related to the regulation of BDNF-TrkB-PI3K/AKT signaling and JAK1/STAT3 signaling, respectively." (PMID 36293548, 2022). "As a result, STAT3 ablation may activate other intrinsic neuroprotective pathways, notwithstanding the decrease in A2-like astrocyte formation, which comprehensively benefits the outcomes of stroke." (PMID 34645472, 2021). "Finally, our data suggest that aberrant gene regulation as a consequence of chronic Stat3 oxidation has the propensity to impact on diseases of the cardiovascular system, such as cardiac insufficiency or stroke, as well as those of the immune system, notably HIES." (PMID 33332446, 2020). "Therefore, the rigid contribution of activated STAT3 after stroke remains incompletely explored." (PMID 31827699, 2019).
Stroke (continued). "Several groups have shown that the STAT3 is activated in vitro and in vivo experimental models of stroke and subsequently activated STAT3 promotes numerous genes responsible for many cellular functions that may play a critical role in both neural injury and repair." (PMID 28923114, 2017). "Thus, the precise contribution of STAT3 activation after stroke remains incompletely understood." (PMID 28923114, 2017). "Studies on stroke have shown increased phosphorylation levels of JAK2 and STAT3 in the cortical and striatal regions of rat brains." (PMID 38887610, 2024). "Post-stroke, neurons release soluble Fas ligand (sFasL), which activates the phosphorylation cascade of the JAK2/STAT3/NF-κB pathway." (PMID 38887610, 2024). "However, the precise role of JAK2/STAT3 activation after stroke remains unclear." (PMID 36419252, 2023). "IL‐6 is a cytokine engaged in the proinflammatory process after stroke, which is mediated by the Janus kinase 2 (JAK2) and the signal transducer and activator of transcription 3 (STAT3) pathway." (PMID 37143406, 2023). "Genes involved in key signaling processes after stroke, including Il-10, Il-12, Hmgb1, Il-13, p38 MAPK, HIF1α, Stat3, and Il-4, were inhibited by NPD1 + RvD1." (PMID 37270727, 2023). "Resveratrol considerably improved neurological function and inhibits the apoptosis of neuron cells after stroke, which is partially induced by activation of the JAK2/STAT3/PI3K/AKT/mTOR signaling pathway." (PMID 36278158, 2022). "The high expression of serum miR-155, tyrosine protein kinase 2/STAT-3 and TNF-α in patients with AIS can trigger the inflammatory response after stroke, and miR-155 can be used as a potential inflammatory marker of AIS." (PMID 36275741, 2022). "The research group confirmed that catalpol promotes angiogenesis and maturation after stroke, which is closely related to the upregulation of VEGF/KDR protein expression and the regulation of Jak2/Stat3 signal." (PMID 33505489, 2021). "STAT3, and IL6, have in a number of in vivo studies been suggested to precondition better recovery after stroke in mouse models." (PMID 29518129, 2018). "Furthermore, stroke induction triggers the nuclear translocation of PKM2 in neutrophils, mediating thrombo-inflammatory responses via STAT3 phosphorylation, which aggravates ischemia-reperfusion injury." (PMID 40746532, 2025). "In conclusion, our study demonstrates that after stroke, astrocytes activate PERK and upregulate MANF expression, which inhibits STAT3 phosphorylation, reduces proinflammatory cytokine release, rescues neuronal synapse loss, and promotes the recovery of neurological function in mice." (PMID 40919080, 2025). "Notably, STAT3 activation in our study appeared more pronounced in HDAC1 KD + IFN-γ group than that HDAC1 KD only and Stroke + IFN-γ groups." (PMID 41388741, 2025). "In addition, pathway analysis of our RNA-seq data revealed that TNFα signaling, IL6/STAT3 signaling, and epithelial–mesenchymal transition (EMT) gene signatures were increased in PPARα KO stroke brains." (PMID 40362325, 2025). "Our study indicates that after stroke, astrocytes activate PERK and upregulate MANF expression, which inhibits STAT3 phosphorylation, reduces the release of pro-inflammatory cytokines, rescues neuronal synapse loss, and promotes the recovery of neurological function in mice." (PMID 40919080, 2025). "The role of STAT3 in mediating the effects of VEGF on endothelial cells and, among others, its involvement in the control of angiogenetic processes and matrix remodeling after strokes, provide further biological plausibility to this association." (PMID 37012328, 2023). "Global pharmacological inhibition of STAT3 exacerbates ischemic brain damage following stroke, however it is not clear which cell type(s) mediate this effect." (PMID 36293020, 2022). "Of note, STAT3 activation primarily occurred during the reperfusion phase rather than during the ischemic phase of stroke." (PMID 33514001, 2021).
Stroke (continued). "Mice lacking STAT3 in astrocytes also show reduced astrogliosis in animal models of traumatic brain injury, and stroke." (PMID 28700615, 2017). "Based on the literature and our previous studies, miR-155 inhibition could potentiate IL-10/STAT-3-mediated AIR, which could significantly contribute to improved post-stroke recovery reported in our previous study." (PMID 27829437, 2016). "Furthermore, NLRP3 inflammasome activation after stroke may be related to the induction of cytokine storm-related proinflammatory cytokines, which can be relieved by Rux via its targeting of the JAK2/STAT3 pathway." (PMID 34367186, 2021). "In the same study it was shown that the vasculature of the stroke mice changed to a non-capillary large vessel phenotype in the STAT3 endothelial knockout stroke mice, suggesting that IL6 production of nearby cells, for example pericytes, would contribute to tissue recovery after stroke." (PMID 29518129, 2018). "Thus, it is possible that IFNAR1 signaling induces STAT3 activation, leading to the suppression of tPA-enhanced inflammatory molecules, IL-1α, IL-1β and CD86, expression and the promotion of anti-inflammatory molecules, Arg1 and CD206, upregulation in MG in delayed tPA-treated stroke animals." (PMID 37063896, 2023). "Notably, in some experimental conditions, curcumin and resveratrol may activate rather than inhibit STAT3 functions, and the acute activation of STAT3 by these drugs during stroke and myocardial infarction promotes cell survival." (PMID 31588227, 2019). "We show that a reduction, in contrast to full-knock-out, of endothelial STAT3 levels is sufficient to double infarct size in the acute phase, 1 day following MCAO, demonstrating tissue-protective effects of STAT3 independent of post-stroke angiogenesis." (PMID 36293020, 2022). "However, endothelial STAT3-mediated angiogenesis (observed 28 days post MCAO), a key feature of long-term stroke recovery, is independent of VEGF signaling." (PMID 36293020, 2022). "In a study on endothelial cells conditionally lacking STAT3, the major transcription factor regulated by IL6, increased infarct volumes and reduced neo-vascularisation leads to impaired motor function in the mice after stroke." (PMID 29518129, 2018).
esophageal cancer (107 papers, 2013 to 2026). A primary or metastatic malignant neoplasm involving the esophagus. "Another active Danshen component, cryptotanshinone, influences the Janus kinase-2/STAT3 signaling pathway, causing esophageal cancer cells to undergo apoptosis." (PMID 38146460, 2023). "Our results showed that STAT3 levels were negatively associated with cancer-associated fibroblasts (CAFs) in patients with esophageal carcinoma (ESCA)." (PMID 36977736, 2023). "This study provides insight into the mechanisms underlying the reciprocal regulation between STAT3 and miR-181b to regulate the proliferation of esophageal cancer cells with cancer stem-like cells properties via the CYLD pathway." (PMID 27189061, 2016). "STAT3 activation by LPS is associated with esophageal cancer and Alzheimer’s disease." (PMID 40843171, 2025). "Therefore, the Stat3/Bcl-2 pathway-mediated apoptosis underlies the cell-type-specific drug sensitivity, suggesting metformin possesses a therapeutic activity and selectivity on esophageal cancer." (PMID 32258099, 2020). "While previous literature indicated that PLK1 modulates STAT3 transcription via β-catenin in esophageal cancer cell lines, our results showed that siRNA-mediated PLK1 knockdown only moderately reduced STAT3 transcription." (PMID 41539998, 2026). "Thereby, phloridzin repressed the progression of oesophageal cancer by acting as an antagonist to the JAK2/STAT3 signaling pathway." (PMID 40761486, 2025). "The mechanism behind the stimulation of apoptosis and prevention of cell proliferation in esophageal cancer cells has been attributed to a CPT-mediated downregulation of STAT3." (PMID 38397437, 2024). "Activated STAT3 acts as an oncogene in esophageal cancer by promoting cell viability, tumor angiogenesis, and metastasis." (PMID 38273295, 2024). "Previous studies have shown that GSK3β functions in the phosphorylation-dependent activation of STAT3 and that inhibition of GSK3β attenuates the progression of gastric and esophageal cancers by suppressing STAT3 activity." (PMID 38318525, 2024). "The inhibition of ERK1/2 in esophageal cancer activated STAT3 and the activation of STAT3 reversed the therapeutic effect of ERK1/2, resulting in drug resistance." (PMID 36890454, 2023). "silencing of RAI14 inhibits the proliferation and invasion of BC cells and the progression of esophageal cancer (EC) through the STAT3 pathway." (PMID 36823639, 2023). "This study demonstrated that root bark glycosides antagonize the JAK2/STAT3 signaling pathway, which can inhibit the development of esophageal cancer." (PMID 38273848, 2023). "STAT3 activation has been widely described in CNS and other malignancies, including hepatocellular, breast, or esophageal carcinoma." (PMID 37762522, 2023). "Zhou C. and colleagues have shown that downregulation of STAT3 induces G1-cell cycle arrest and apoptosis in esophageal carcinoma." (PMID 37033189, 2023). "Activation of the transcription factor STAT3 was recently linked to CRT resistance in other gastrointestinal cancers such as rectal and esophageal cancers, but its role in PDAC needs to be clarified." (PMID 35267609, 2022). "In conclusion, our research revealed that CXCL12/CXCR7 regulates EMT and other malignant processes by activating the STAT3 pathway to accelerate the growth and metastasis of esophageal cancer." (PMID 35264069, 2022). "We have recently shown that increased STAT3 activity correlates with chemoradiotherapy resistance in rectal and esophageal cancer cells, and that inhibition of the IL-6/STAT3 pathway results in sensitization to CRT." (PMID 35267609, 2022). "Most esophageal cancer cell lines showed prominent expression of STAT3 and some of them even showed constitutive phosphorylation of STAT3." (PMID 33530306, 2021). "For example, Let-7 affected the sensitivity of cisplatin by IL-6/STAT3 pathway in esophageal cancer." (PMID 34096570, 2021).
esophageal cancer (continued). "Aurora A enhances Stat3 activity while Aurora A knockdown reduces the Stat3 nuclear translocation in gastric and esophageal cancers." (PMID 34715887, 2021). "A recent study in squamous cells of an esophagus carcinoma model shows that these cells present increased STAT3 phosphorylation and signaling due to a constitutive activation of ERK, which promotes the degradation of STAT1 via the proteasome." (PMID 34925319, 2021). "Studies showed that NSC74859 and stattic, two inhibitors of STAT3, enhanced radiosensitivity by inhibiting hypoxia- and radiation-induced STAT3 activation in esophageal cancer." (PMID 32733808, 2020). "We found that the expression level of both STAT3 and p-STAT3 was higher in clinical esophageal cancer tissue than in the adjacent normal tissue, using western blot and qPCR analysis." (PMID 33390934, 2020). "S3I-201 (NSC 74859) is a selective chemical probe inhibitor of STAT3 and binds to the STAT3 phosphotyrosine peptide (PY*LKT) with the potential to become a radiosensitizer for esophageal cancer radiotherapy." (PMID 32872659, 2020). "Another study has verified that the progression of esophageal cancer was promoted by XIST-regulated miR-494/CDK6 axis to activate the JAK2/STAT3 signal pathway." (PMID 32127028, 2020). "In this study, we found that p-STAT3 (Tyr705) was upregulated in clinical esophageal cancer samples." (PMID 33390934, 2020). "In summary, we demonstrated that STAT3 is overexpressed in clinical esophageal cancer samples by RNA sequencing." (PMID 33390934, 2020). "Previous studies have reported that STAT3 inhibitors have effects on cancers, such as pancreas and esophagus cancers." (PMID 32641132, 2020). "STAT3 is constitutively activated by tyrosine phosphorylation in numerous cancers, including esophageal cancer." (PMID 33390934, 2020). "Overexpression of Stat3 has been reported in human esophageal carcinoma, and it is related to malignancy and prognosis of the tumor." (PMID 32258099, 2020). "In this study, we evaluated the antiapoptosis effects of metformin on esophageal carcinoma cells and normal epithelial cells in the in vitro model and investigated the role of Stat3 signaling and intracellular ROS." (PMID 32258099, 2020). "Herein, we investigated the functional effects of STAT3 down-regulation in ECA109 to illustrate the role of STAT3 in esophageal cancer." (PMID 29636641, 2018). "In the present study, we targetedly down-regulated the expression of STAT3 in esophageal cancer ECA109 cell line using STAT3-specific shRNA vector pSi-STAT3 plasmid and investigated the effects of STAT3 down-regulation on ECA109 cells." (PMID 29636641, 2018). "To explore the biological role of STAT3 in esophageal cancer, we used small hairpin RNA to knockdown the expression of the STAT3 gene in the esophageal carcinoma ECA109 cell line and the cell apoptosis, cell cycle and cell migration were investigated." (PMID 29636641, 2018). "In summary, our study presents several evidences to support STAT3 as a potential target for esophageal cancer therapy." (PMID 29636641, 2018). "The study also demonstrated that RNA interference mediated PLK1 RNA inactivation led to a decrease in STAT3 transcriptional activity in esophageal cancer cells." (PMID 29983892, 2018). "One study in esophageal cancer revealed that STAT3 and PLK1 control each other’s transcription in a positive feedback loop." (PMID 29983892, 2018). "To determine if downregulation of p-STAT3 decreases apoptosis in esophageal carcinoma cells, we further investigated the levels of proteins involved in the MAPK signaling pathway." (PMID 30186159, 2018). "In this study, we demonstrated for the first time that CYT-Rx20 suppressed the PI3K/AKT and STAT3 signaling pathways and inhibited esophageal cancer cell viability and migration." (PMID 27875549, 2016).